SIK2 (salt inducible kinase 2)
Diseases named in the same sentence as SIK2 in open-access papers (continued):
Sharing a sentence is not in itself a finding about the gene and the disease.
ovarian carcinoma (continued). "SIK2 activity is associated with the autophosphorylation level of S358, a key residue regulating SIK2 protein stability, and MRIA9 significantly reduced SIK2 S358 autophosphorylation, SIK2 activity, and ovarian cancer cell metastasis." (PMID 36731029, 2023). "In addition, in the ovarian cancer cell line SKOv3, overexpression of SIK2 was found to induce centrosome splitting by phosphorylating the centrosome linker protein C-Nap1." (PMID 37854071, 2023). "Moreover, SIK2 involves various disorders, especially ovarian cancer, by different proliferative and anti-apoptotic mechanisms." (PMID 34751020, 2022). "Under the activation of SIK2 overexpressed in ovarian cancers, Nap‐S in the hydrogel is phosphorylated to yield hydrophilic Nap‐Phe‐Phe‐Glu‐Glu‐Leu‐Tyr‐Arg‐Thr‐Gln‐Ser(H2PO3)‐Ser‐Ser‐Asn‐Leu (Nap‐Sp), triggering the disassembly of the hydrogel and a responsive release of the inhibitor." (PMID 35618488, 2022). "Upon activation by salt‐inducible kinase 2 (SIK2) overexpressed in ovarian cancers, hydrogelators in the HG‐9‐91‐01‐coassembled nanofibers will be efficiently converted to their hydrophilic phosphates, triggering the disassembly of the nanofibers and the sustained release of HG‐9‐91‐01." (PMID 35618488, 2022). "In ovarian cancer, SIK2 upregulates HIF-1α, which then increases glycolytic enzyme HK2 translation." (PMID 36230617, 2022). "Moreover, SIK2 protein expression was positively correlated with the expression of MYLK‐pS343 in ovarian cancer cell lines and tissues." (PMID 35278271, 2022). "Targeting SIK2 presents a novel therapeutic strategy for preventing ovarian cancer metastasis." (PMID 35278271, 2022). "Moreover, UCA1 sponged the miR-654-5p and upregulated the expression of its target SIK2 in ovarian cancer cells." (PMID 36105363, 2022). "Furthermore, SIK2 has been identified as a centrosome kinase regulating the G2-M transition, and its depletion or inhibition sensitizes ovarian cancer to paclitaxel-based chemotherapy." (PMID 34359562, 2021). "Remarkably, high expression levels of SIK2 in ovarian cancer suggest a role in tumor progression." (PMID 34359562, 2021). "Consistent with this, we found that the long-term inhibition of SIK2 using MRIA9 significantly enhanced the chromosome number of SKOV-3 and OVCAR-3 cells, suggesting that SIK2 may play a critical role in maintaining genomic stability in ovarian cancers." (PMID 34359562, 2021). "SIK2 upregulates the expression level of HIF-1α, which enhances the transcription of glycolysis-associated genes (HK2 and PFKL), inducing the metastasis and invasion of ovarian cancer." (PMID 35004308, 2021). "Based on the role of SIK2 in accurate spindle positioning, we hypothesized that SIK2 inhibition might lead to chromosomal instability in ovarian cancer cells." (PMID 34359562, 2021). "Previous siRNA screen identified SIK2 as a regulator of G2/M progression in ovarian cancer." (PMID 34359562, 2021). "Notably, a recent study reported that SIK2 is overexpressed in ovarian cancer metastasis in the omentum, an adipocyte-rich abdominal cavity representing the predilection site for ovarian metastasis." (PMID 34359562, 2021). "Furthermore, as a centrosome kinase, SIK2 has been shown to regulate the G2/M transition, and its depletion sensitizes ovarian cancer to paclitaxel-based chemotherapy." (PMID 34359562, 2021). "Next, we asked whether blocking SIK2 activity using MRIA9 enhances the paclitaxel response of 3D-primary cancer cell cultures derived from patients diagnosed with ovarian cancer." (PMID 34359562, 2021). "All these findings suggest that the inhibition of SIK2 may present a novel and promising therapeutic avenue for ovarian cancer treatment, hence the need to develop new potent and selective SIK2 inhibitors." (PMID 34359562, 2021).
ovarian carcinoma (continued). "SIK2 also functions as a centrosome kinase that regulates centrosome splitting during mitosis in ovarian cancer cells, indicating that its depletion could inhibit cancer growth by targeting multiple phases of the cell-cycle such as G1 arrest." (PMID 32082487, 2020). "However, the role of SIK2 in the regulation of lipid synthesis in cancer cells, especially in ovarian cancer (OC) cells, is still unclear." (PMID 31932581, 2020). "Consistent with these clinical observations, we also showed that the forced expression of SIK2 enhances the metastatic ability of ovarian cancer cells in the intraperitoneal cavity, whereas SIK2 depletion prevents the formation of peritoneal disseminated tumors in in vivo mouse models." (PMID 30568223, 2019). "Therefore, SIK2 would be regard as a potential target for ovarian cancer diagnosis and treatment." (PMID 39256355, 2024). "Hence, it has been proposed that SIK2 is a crucial oncogenic element in human ovarian cancer." (PMID 34751020, 2022). "Several studies have demonstrated that SIK2 is a centrosome kinase involved in mitosis regulation by facilitating centrosome separation during the G2 phase, and preclinical studies have reported the impact of SIK2 depletion in boosting the sensitivity of ovarian cancer cells to paclitaxel treatment." (PMID 34359562, 2021). "MRIA9 revealed a new role of SIK2 in promoting the establishment of an accurate cell division plane through orchestrating the centrosome alignment and spindle position during the cell division and thus suggesting a role of SIK2 in maintaining chromosomal stability in ovarian cancer." (PMID 34359562, 2021). "SIK2 activation also increased AMPK-induced acetyl Coa carboxylase phosphorylation, which accelerated ovarian cancer progression." (PMID 39256355, 2024). "Adipocytes activate SIK2 via the phospholipase/Ca2+ transduction pathway, which augments PI3K-Akt signaling and acetyl-CoA carboxylases (ACC) phosphorylation in ovarian cancer cells." (PMID 36731029, 2023). "SIK2 plays a role in the phosphorylation of p85α, ACC eventually upregulates FA oxidation, and the PI3-AKT pathway stimulates the growth of ovarian cancer cells by releasing free radicals in the cell's microenvironment making the cell even more cancerous." (PMID 37845675, 2023). "Taken together, our data showed that SIK2 accelerates ovarian cancer cell motility and metastasis by promoting MYLK/MYL2 phosphorylation and that targeting SIK2 inhibits ovarian cancer metastasis in vivo." (PMID 35278271, 2022). "To exclude potential off-target effects of SIK2 inhibitors, we knocked out endogenous SIK2 by CRISPR/Cas9 and established stable ectopic expression of SIK2 in SKOv3 and OVCAR8 ovarian cancer cells." (PMID 35642638, 2022). "SIK2 directly phosphorylated MYLK at Ser343 and activated its downstream effector MYL2, promoting ovarian cancer cell motility and metastasis." (PMID 35278271, 2022). "We found that SIK2 promotes MYLK mediated MYL2 phosphorylation, cell motility and metastasis in ovarian cancer." (PMID 35278271, 2022). "The released HG will in turn down‐regulate SIK2 activity and consequently inhibit its downstream proteins (e.g., mTOR, DRP1, and ACC1) to efficiently suppress ovarian cancer proliferation and metastasis." (PMID 35618488, 2022). "SIK2 and MYLK‐pS343 were highly expressed in 41% (59/144) and 37% (53/144) of the epithelial ovarian cancer cases, respectively (P = 1.06e‐08)." (PMID 35278271, 2022). "Our results also revealed that SIK2 directly phosphorylates MYLK at Ser343, suggesting that SIK2 enhances cell motility and metastasis by directly phosphorylating MYLK and activating MYLK/MYL2 signalling in ovarian cancer." (PMID 35278271, 2022). "In this study, we demonstrated that SIK2 regulates cell motility, migration and metastasis by phosphorylating MYLK in ovarian cancer." (PMID 35278271, 2022).
ovarian carcinoma (continued). "Our study results showed that SIK2 regulates ovarian cancer cell motility and metastasis, and that SIK2 inhibition attenuates metastasis and reduces MYL2 phosphorylation in ovarian cancer." (PMID 35278271, 2022). "Findings from a recent study that we conducted showed that SIK2 is required for centrosome splitting in the mitosis of ovarian cancer cells and that ARN‐3236 inhibited SIK2 and sensitized ovarian cancer cells to paclitaxel." (PMID 35278271, 2022). "We then analyzed the expression levels of SIK2, phosphorylated MYL2 and phosphorylated MYLK in ovarian cancer cell lines (SKOV3, OVCAR8, OVCAR5, OVCAR3 and OVISE) and human breast cancer cell lines (MDA‐MB‐231 and Hs578 t)." (PMID 35278271, 2022). "The potential of our new SIK2 inhibitor, MRIA9, was also demonstrated in 3D- spheroid assays of two ovarian cancer cell lines, SKOV-3 and OVCAR-3, and in primary ovarian cancer cells originating from different patients." (PMID 34359562, 2021). "In ovarian cancer cells, UCA1 can induce SIK2 expression via endogenous sponging of miR-654-5p and thus antagonize chemosensitivity to PTX." (PMID 34512721, 2021). "The up-regulation of salt inducible kinase 2 (SIK2) reversed the inhibitory effect of miR-149-5p on PTX resistance and cell progression in PTX-resistant ovarian cancer cells, indicating that miR-149-5p enhanced PTX sensitivity by targeting SIK2." (PMID 34722295, 2021). "Some literatures manifested that SIK2 acted as the oncogene and the crucial regulator of glucose metabolism in ovarian cancer cells through PI3K/AKT/HIF-1α pathway, and SIK2 acted as a critical regulator of lipid synthesis and promotes ovarian cancer growth." (PMID 33344445, 2020). "Our previous research demonstrated that SIC-19, an innovative inhibitor of salt-inducible kinase 2 (SIK2), effectively reduces SIK2 protein levels through the ubiquitin-proteasome pathway and exhibits synthetic lethal effects with poly ADP-ribose polymerase (PARP) inhibitors in ovarian cancer." (PMID 40612876, 2025). "Additionally, SIK2 phosphorylates MYLK at Ser343, and p-MYLK subsequently phosphorylates MLC2, thereby modulating cytoskeletal motility and promoting ovarian cancer invasion and metastasis." (PMID 40612876, 2025). "Salt-inducible kinase 2 (SIK2) may promote MR of glucose through the PI3K/AKT/HIF-1α pathway and Drp1-mediated mitochondrial fission in ovarian cancer." (PMID 39588377, 2024). "Additionally, the AMP kinase-related protein, salt-inducible kinase 2, upregulates SREBP-1 and SREBP-2 in ovarian cancer cells, through increased fatty acid and cholesterol synthesis, demonstrating a regulatory role of SREBP-2 through PI3K/Akt signaling." (PMID 37986175, 2023). "In summary, circCELSR1 could target miR-149-5p/SIK2 axis and facilitated PTX resistance in ovarian cancer." (PMID 38152652, 2023). "ARN-3261 preferentially targets SIK2 and SIK3 (IC50 of 11 and 19 nM, respectively) and has been shown to sensitize ovarian cancer cell lines and xenografts to carboplatin and is currently in Phase 1a/1b clinical trials in patients with ovarian, peritoneal and other solid tumors." (PMID 36731029, 2023). "Furthermore, SIK‐2 can also directly phosphorylate MYLK and activate its downstream pathway to boost ovarian cancer cell motility." (PMID 37605299, 2023). "In addition, we found that adipocytes induced SIK2 phosphorylation at Ser358 and MYLK phosphorylation at Ser343, enhancing ovarian cancer cell motility." (PMID 35278271, 2022). "We have found that SIK2 inhibitors enhance response to PARP inhibitors in ovarian cancer and TNBC cell lines and xenografts, independent of BRCA mutation status." (PMID 35642638, 2022). "Interestingly, the ABCB1 was directly targeted by miR-129, while miR-654-5p targeted Salt inducible kinase 2 (SIK2) which is known to promote metabolism and metastasis in ovarian cancer." (PMID 34204094, 2021).
ovarian carcinoma (continued). "Similarly, tumor suppressors miR-136, miR-383-5p, and miR-874 have been reported to conquer PTX resistance of ovarian cancer cells by silencing NOTCH3, tripartite motif containing 27 (TRIM27), and salt inducible kinase 2 (SIK2), respectively." (PMID 34512721, 2021). "Coincidentally, both SIK2 and YAP have been proven to be oncogenes in ovarian cancer." (PMID 30723708, 2019). "Additionally, although SIK2 has been reported to promote centrosome separation in ovarian cancer cells by phosphorylating C‐Nap1,38 our study found no notable cell cycle distribution changes in non‐irradiated SIK2 knockdown CRC cells compared to controls." (PMID 39877288, 2025). "In addition to facilitating SIK2 degradation, this compound decreases RAD50 phosphorylation, impairs the nuclear translocation of RAD50, and when used with PARP inhibitors, has a synergistic cytotoxic effect on ovarian cancer." (PMID 40612876, 2025). "SIK2 autophosphorylation at S358 regulates its stability in adipocytes, but not activity, and this may be of particular relevance in ovarian cancer cells where very high levels of SIK2 are found." (PMID 36731029, 2023). "Although our study provides new insights into the role of SIK2 in cell motility and metastasis in ovarian cancer, we did not confirm whether high expression of SIK2 play a similar role in other disease sites." (PMID 35278271, 2022). "However, the mechanisms by which SIK2 regulates cancer cell motility and metastasis in ovarian cancer (OC) have not been fully described." (PMID 35278271, 2022). "However, the mechanisms by which SIK2 regulates cancer cell motility, migration and metastasis in ovarian cancer have not been fully discovered." (PMID 35278271, 2022). "SIK2 inactivation in SKOV-3 raised the mean chromosome number from 47.54 to 76.86, while in OVCAR-3, the number of chromosomes increased from 58.83 to 71.26, respectively, demonstrating that inhibition of SIK2 activity promoted chromosomal instability in ovarian cancer." (PMID 34359562, 2021). "Interestingly, SIK2 is highly expressed in metastatic deposits in ovarian cancer but not in ovarian primary lesions promoting abdominal metastasis while SIK2 depletion was shown to prevent metastasis in vivo." (PMID 32082487, 2020).
breast carcinoma (13 papers, 2018 to 2025). "Reports of a deletion in 11q23, where SIK2 gene is localized, in a breast cancer patient cohort and significant loss of SIK2 copy numbers in TCGA dataset query are in line with reduced SIK2 expression in breast tumors." (PMID 29774109, 2018). "Since our in vitro and in vivo data indicated a negative correlation between SIK2 levels and breast cell proliferation and survival, we next asked if SIK2 levels are associated with survival of breast cancer patients." (PMID 29774109, 2018). "Kaplan-Meier analysis showed that higher SIK2 levels are significantly associated with better RFS in all patients including different subtypes of breast cancer (n=1635)." (PMID 29774109, 2018). "Strikingly, patient survival analysis indicated that higher levels of SIK2 are significantly associated with better survival, especially in basal breast cancer cases." (PMID 29774109, 2018). "These outcomes support our in vitro findings and indicate that SIC-19 causes DNA damage in the animal model and degrades the endogenous SIK2 protein, increasing the sensitivity of breast cancer cells to olaparib." (PMID 40612876, 2025). "SIK2 inhibition sensitizes ovarian and breast cancer cells by enhancing olaparib-mediated inhibition of PARP enzyme activity." (PMID 35642638, 2022). "In all breast cancer combined, high mRNA expression of SIK2 pre-chemotherapy correlated with reduced mortality." (PMID 34084284, 2021). "SIK2 (salt inducible kinase 2) was a potential breast cancer suppressor, and compared with normal control, its expression level of breast cancer tissues and cell lines was reduced." (PMID 32095316, 2020). "The researchers also found SIK2-mediated attenuation of proliferation and survival of breast cancer cells with parallel inhibition of the Ras-Erk and PI3K-Akt pathways." (PMID 30723708, 2019). "In vitro loss- and gain-of-function experiments combined with xenograft studies demonstrated that SIK2-mediated attenuation of proliferation and survival of breast cancer cells with parallel inhibition of both Ras/Erk and PI3K/Akt pathways." (PMID 29774109, 2018). "Altogether, these findings suggest that SIK2 inhibits migration and invasion in breast cancer cell lines via blocking EMT." (PMID 29774109, 2018). "Here, we report the reduced levels of SIK2 expression in breast cancer tissues and in breast cancer cell lines suggesting a tumor suppressor role for SIK2 in breast cancer." (PMID 29774109, 2018). "This inverse correlation is in agreement with our in vitro findings suggesting SIK2 is a negative regulator of proliferation in the context of breast cells and it acts as a potential tumor suppressor in breast cancer progression." (PMID 29774109, 2018). "In vitro loss-of-function and gain-of-function experiments combined with xenograft studies demonstrate that SIK2 attenuates proliferation and survival responses of breast cancer cells with concomitant inhibition of Ras/Erk and PI3K/Akt pathways." (PMID 29774109, 2018). "Our findings elucidated that SIK2 has also an inhibitory role in migration/invasion ability of breast cancer cells through regulation of epithelial mesenchymal transition." (PMID 29774109, 2018). "Based on our in vitro and in vivo functional analyses combined with patients’ tumor analyses, we propose SIK2 as a novel tumor suppressor and a potential biomarker for breast cancer." (PMID 29774109, 2018). "The METABRIC (EGAS00000000083) dataset which comprises clinic-pathology data from discovery (n=997) and validation sets of primary breast tumors (n=995), revealed a significantly lower SIK2 expression in breast cancer tissues than in normal samples (n=144)." (PMID 29774109, 2018). "Here, we report SIK2 as a potential tumor suppressor in breast cancer whose expression was reduced in tumor tissues and breast cancer cell lines compared to normal counterparts." (PMID 29774109, 2018).